BRCA2 (BRCA2 DNA repair associated)
Diseases named in the same sentence as BRCA2 in open-access papers (continued):
Sharing a sentence is not in itself a finding about the gene and the disease.
pancreatic cancer (continued). "In particular, 6 families (one of which BRCA1 positive) showed three pancreatic cancer cases, and 31 families (4 of which BRCA1 positive and 2 of which BRCA2 positive) showed two pancreatic cancer cases." (PMID 30736435, 2019). "Human pancreatic cancer cells lines (BxPC-3, CFPAC-1) were exposed to 0.5μM pimasertib under hypoxia (3% 02) for 4 hours and downregulation of BRCA2 protein expression was observed upon MEK inhibition whereas BRCA1 expression was unaffected (data not shown)." (PMID 29545922, 2018). "Among 178 CDKN2A mutation carriers, PDAC was found in 7.3% (N = 13), 0.9% in the familial pancreatic cancer group (N = 2; 1 advanced PDAC, 1 grade 2 neuroendocrine tumour [NET]) and 1 PDAC was diagnosed among BRCA2 carriers." (PMID 29069866, 2017). "Nucleotide sequencing of BRCA2 in lymphocyte and tumoral DNA of a 50-year-old male who presented with an androgen-secreting ACC and a strong family history of breast, ovarian, and pancreatic cancers." (PMID 27603373, 2016). "Among 190 pancreatic cancer patients, the positive yield was 10.5% (n = 20), and positive results were most commonly identified in ATM (40.0%; 8/20), BRCA2 (25.0%; 5/20), and PALB2 (15.0%; 3/20)." (PMID 26681312, 2016). "In pancreatic cancer, autoantibody frequency to three TAAs (PARP1, BRCA1 and BRCA2) were 0% (0/41), 7.3% (3/41) and 0% (0/41)." (PMID 25865228, 2015). "Thus, germline mutations in the BRCA2, p16/CDKN2A, STK11, and PRSS1, that are responsible for familial breast cancer, Familial atypical multiple melanoma, Peutz-Jeghers and Familial pancreatitis, respectively, have been clearly associated with an increase risk of pancreatic cancer." (PMID 23935836, 2013). "In agreement with BRCA2-related function of the PALB2, pancreatic cancer xenografts obtained from a PALB2 carrier demonstrated pronounced sensitivity to cisplatin and mitomycin C." (PMID 21819606, 2011). "A study showed that WEE1 inhibition sensitized BRCA2 wild-type but not BRCA2 mutant cancer cells to gemcitabine-based chemoradiation in pancreatic cancer cells." (PMID 41354716, 2025). "As described in the pancreatic cancer section, in this phase 2 trial, the ORR for rucaparib in germline BRCA2 (41%) was similar to that in germline PALB2 (50%) and somatic BRCA2 (50%), suggesting a similar benefit with PALB2 mutations, although the limitation was that numbers were low." (PMID 39796639, 2024). "Pancreatic cancer is another common BRCA-associated cancer; however, multiple studies have shown that BRCA2, but not BRCA1, predisposes individuals to pancreatic cancer." (PMID 36861435, 2023). "The risk for pancreatic cancer in individuals with pathogenic variants of BRCA1, BRCA2, PALB2, or ATM but without a history of pancreatic cancer has not been elucidated." (PMID 35163129, 2022). "By panel testing, pancreatic cancer occurs in 0–3% for BRCA1 and 1–6% for BRCA2." (PMID 35454911, 2022). "For example, the DDR genes BRCA1, BRCA2 and ATM, or PALB2, each one usually found mutated in no more than 3.5% of cases, increase pancreatic cancer risk when altered at the germline level." (PMID 35563100, 2022). "In pancreatic cancer, BRCA1 and BRCA2 have a prevalence of 1.7 and 4.5%, respectively." (PMID 34979999, 2022). "Due to the specific potential clinical relevance of the use of olaparib-based combinations in pancreatic cancer and the fact that olaparib and TRAIL demonstrated the strongest synergistic effect in CAPAN1 and BRCA2/CIN, these cells were used for further mechanistic studies." (PMID 36358659, 2022). "Further, BRCA1, BRCA2 and PALB2 mutant pancreatic cancer frequently shows signature 3, and the presence of signature 3 is predictive of response to platinum chemotherapy in patients with advanced pancreatic cancer." (PMID 34572943, 2021).
pancreatic cancer (continued). "In total, 113 consecutive individuals with personal or family history of breast, ovarian, or pancreatic cancer and without P/LP variants in BRCA1 and BRCA2 genes were analyzed." (PMID 32957588, 2020). "BRCA2, Smad4, EGFR genes play important role in pancreatic cancer pathway." (PMID 30792708, 2019). "Particularly, the age for pancreatic cancer diagnosis in BRCA1 families is significantly lower than in BRCA2 families and general populations, whereas short-term prognosis for patients in BRCA2 families is significantly better than for other groups of patients." (PMID 30736435, 2019). "Our therapy also appears to be highly effective for eradicating other types of cancers which express varying levels of FRα, including breast and pancreatic cancers expressing WT and/or mutant BRCA1 and/or BRCA2 (Schutsky and Powell, 2014, unpublished observations)." (PMID 26359629, 2015). "The colorectal cancer risk, however, has not been consistently replicated, while the prostate and pancreatic cancer risks are lower than in BRCA2 carriers." (PMID 18349832, 2008). "The role of polymerase theta inhibition in pancreatic cancers with BRCA1/BRCA2 and non-BRCA HR defects and possibly defects in other repair pathways could be the logical step for investigation in future trials." (PMID 36975505, 2023). "Inactivation of Brca2 does not promote murine pancreatic cancer formation on its own." (PMID 35163129, 2022). "The NCCN clinical practice guideline in genetic high-risk assessment for breast, ovarian, and pancreatic cancer does not recommend pancreatic cancer screening for BRCA1 and BRCA2 mutation carriers in the absence of a close family history of exocrine pancreatic cancer." (PMID 32655641, 2020). "To determine if the role of PALB2 as a linker between BRCA1 and BRCA2 is critical for BRCA1/2-mediated tumor suppression, we generated Palb2 mouse pancreatic cancer models and compared tumor latencies, phenotypes and drug responses with previously generated Brca1/2 pancreatic cancer models." (PMID 31877165, 2019). "Genetic alterations in tumor suppressor genes found in lower frequency (<10%) in pancreatic cancer include STK11/LKB1, MKK4, TGFβ R1 (ALK 5, chromosome 9q), TGFβ R2 (chromosome 3p), ACVR1β (ALK 4, chromosome 12q), ACVR2 (chromosome 2q), FBXW7 (CDC4), EP300, BRCA2, ATM, and AKT2." (PMID 24624093, 2014). "Our results provide a preclinical rationale for the combination of PARP inhibitors and TRAIL receptor agonists for the treatment of pancreatic cancer and suggest that the use of PARP inhibitors could be extended to patients without BRCA2 mutations if used in combination with TRAIL agonists." (PMID 36358659, 2022). "Recently, it was demonstrated that heterozygosity for Brca2 is sufficient to promote carcinogenesis in a murine model of familial pancreatic cancer and also that LOH might not be essential for human pancreatic ductal carcinogenesis in BRCA2 999del5 mutation carriers." (PMID 21958427, 2011). "The incidences of pancreatic cancer in male relatives of BRCA1 carriers, BRCA2 carriers, and non-carriers were 1.4%, 2.7%, and 0.6%, respectively." (PMID 36861435, 2023). "In our study, there were 4 cases of pancreatic cancers among 20 BRCA1 and BRCA2 carriers, 2.5 times the frequency in the group with no pathogenic variants identified." (PMID 35155181, 2021). "BRCA2 protein levels were not affected by miR-19a or miR-19b in the BxPC-3 and MIA PaCa-2 pancreatic cancer cell lines." (PMID 27630665, 2016).
Fanconi anemia (212 papers, 2004 to 2026). Fanconi anemia (FA) is a hereditary DNA repair disorder characterized by progressive pancytopenia with bone marrow failure, variable congenital malformations and predisposition to develop hematological or solid tumors. "Mutations in the BRCA1 (breast and ovarian cancer susceptibility protein 1) and BRCA2 genes, which are associated with an increased risk of breast, ovarian, pancreatic, and prostate cancers, can cause Fanconi anemia and are linked to R-loop stabilization." (PMID 40271193, 2025). "This suggests that the c.681+5G>C variant has a lower impact on BRCA2 function than other BRCA2 deleterious mutations associated with Fanconi anemia." (PMID 39741007, 2025). "While Fanconi Anemia-associated genes BRCA2, FANCA and PALB2 are known PCa GT candidates, FANCD2 outranked FANCA, with FANCG, ECCR4, FANCE and FANCI (in order of ranking) potential candidates." (PMID 41038821, 2025). "Homozygosity for pathogenic BRCA2 variants causes a rare inherited form of bone marrow-associated acute myeloid leukaemia, solid tumours and developmental anomalies termed Fanconi anaemia." (PMID 39438716, 2024). "FANCG, together with established breast/ovarian predisposition genes BRCA1 and BRCA2 belongs to the Fanconi anemia gene family; however, little is known about cancer predisposition in carriers of FANCG germline alterations." (PMID 39149814, 2024). "Biallelic inactivation of BRCA2 (FANCD1) or RAD51C (FANCO) also causes Fanconi anemia (FA), an autosomal recessive disorder due to pathogenic mutations in one of twenty-three identified FANC genes." (PMID 36906610, 2023). "Mutations in BRCA2 are also associated with Fanconi anemia (FA), a rare autosomal-recessive disorder associated with childhood solid tumors and acute myeloid leukemia; consequently, BRCA2 is also considered to be one of the 22 FA genes, FANCD115." (PMID 35365640, 2022). "BARD1, BRIP1, PALB2, RAD50, RAD51C, NBN, and MRE11A gene mutations have been implicated in OC as part of the BRCA2/Fanconi anaemia signalling pathway in the event of nil BRCA1 and/or BRCA2 mutations." (PMID 36231355, 2022). "Here, we report that GR-CDXL1 displays a somatic biallelic mutation in BRCA2 and promoter deletion of Fanconi anemia pathway gene FANCA." (PMID 35511434, 2022). "Carriers of BRCA2 pathogenetic variants should be advised on the risk of Fanconi anemia and/or brain tumors in minor children if BRCA2 variants has been revealed in both maternal and paternal lines." (PMID 35454911, 2022). "Bi-allelic mutations in BRCA2/FANCD1 are at the origin of a subgroup of the rare genetic disease Fanconi anemia, which confers cancer susceptibility in children." (PMID 34359619, 2021). "Fanconi anemia patients carrying BRCA2 mutations (FA-D1) also show predisposition to medulloblastoma brain tumors." (PMID 33923105, 2021). "Fanconi Anemia (FA) genes were mutated in 152 patients, with BRCA2 (4.0%), BRCA1 (3.7%), and BRIP1 (2.8%) mutations occurring most frequently." (PMID 34620846, 2021). "Diverse mechanisms can cause defective BRCA‐like behavior, including inherited mutations in BRCA1, BRCA2, and Fanconi anemia complementation (FANC) group of genes." (PMID 33660437, 2021). "The pathogenic variants c.5609_5610delTCinsA as well as c.7878G>C of the BRCA2 gene were initially described in the context of Fanconi anemia disease." (PMID 34680878, 2021). "In the current study, we analyzed telomere dysfunction in lymphoid cell lines from five BRCA2 999del5 mutation carriers and three Fanconi Anemia D1 patients by fluorescence in situ hybridization (FISH)." (PMID 35052422, 2021). "First, we provide a brief history of BRCA1 and BRCA2, including their identification as cancer predisposition genes and recognition as members in the Fanconi anemia pathway." (PMID 32269964, 2020).
Fanconi anemia (continued). "Due to their involvement in DNA repair, several groups have studied or focused their genome-wide results on variants affecting genes involved in the Fanconi anemia pathway, such as BRCA2/FANCD1, BRIP1/FANCJ, FANCC, FANCE, and REV3L/POLZ." (PMID 32585810, 2020). "Recently, the detection of pathogenic variants in Fanconi anemia DNA damage repair pathway genes, such as BRCA2, BRIP1, FANCC, and FANCE was also reported in familial CRCs34." (PMID 30850667, 2019). "For specific loci reporting genotypes also masks incidental findings, e.g. only homozygous or two different heterozygous (possible compound heterozygous) likely pathogenic variants in BRCA2 will be reported in DDG2P as a cause of Fanconi anemia." (PMID 31147538, 2019). "Of these, about one-quarter (6% of all ovarian, fallopian tube, and peritoneal cancers) are caused by genes other than BRCA1 and BRCA2, including many genes associated with the Fanconi anemia pathway or otherwise involved with homologous recombination." (PMID 30650666, 2019). "It has also been reported that Fanconi Anemia (FA) is caused by biallelic FANCD1/BRCA2 pathogenic variants." (PMID 31060517, 2019). "Carriers of bi‐allelic BRCA2 inactivating variants are affected with Fanconi Anemia (FA), complementation group D1." (PMID 29460995, 2018). "Proteins other than BRCA2 implicated in homologous recombination or the Fanconi anemia repair pathway, like BRCA1, RAD51, PALB2, XRCC3, FANCI, or FANCD2, were at most modestly affected, as were non-homologous end joining proteins like KU80, KU70, and XRCC4." (PMID 28575672, 2017). "We also find that 18 VOUS BRCA1 and BRCA2 variants that are listed in BRCA Exchange are present at least once in the homozygous state in patients who lack features of Fanconi anemia." (PMID 27884173, 2016). "Homozygosity of missense alleles at BRCA2 (FANCD1) leads to Fanconi Anemia and increased cancer susceptibility, notably hematological malignancies." (PMID 27836010, 2016). "Medulloblastomas and other childhood cancers have been described in kindred with Fanconi anemia in the context of oncogenic BRCA2 germline mutations." (PMID 26380221, 2015). "Biallelic mutations of BRCA2 are linked to Fanconi’s anemia, a genetic disorder characterized by congenital abnormalities and a profound increase in cancer predisposition, namely AML." (PMID 26528434, 2015). "The BRCA2 protein is encoded by the BRCA2 gene located on chromosome 13q and functions in the Fanconi anemia pathway, which is partly responsible for genome-maintenance." (PMID 24624093, 2014). "It is interesting that biallelic mutations of BRCA2, the major gene for hereditary breast cancer, were also shown to cause Fanconi anemia." (PMID 25093046, 2014). "PALB2, also known as FANCN, is a Fanconi anemia gene that encodes for a protein that interacts with BRCA2 during homologous recombination and double-strand break repair." (PMID 23586058, 2013). "In another recent study, fibroblasts of BRCA1 and BRCA2 mutation carriers, a BRCA2-deficient fanconi anemia patient and normal individuals were exposed to mammography X-rays and chromosomal anomalies were assessed." (PMID 23936236, 2013). "Biallelic mutations of BRIP1 cause Fanconi anemia complementation group J, a phenotype different to that caused by biallelic mutations in BRCA2, resulting in much lower rate of childhood solid tumours." (PMID 23586058, 2013). "Homozygous mutations in BRCA2 are assumed to be embryonic-lethal mutations or responsible for Fanconi anemia, which is characterized by bone marrow failure, developmental abnormalities, and predisposition to cancer." (PMID 22471976, 2012).
Fanconi anemia (continued). "These biallelic BRCA2 mutations are known to cause the D1 subgroup of Fanconi anemia (FA-D1), a rare autosomal recessive disorder characterized, among other defects, by predisposition to several childhood cancers." (PMID 22923021, 2012). "It has been also documented that the presence of Fanconi anemia/BRCA2 mutations in pancreatic cells is predictive for sensitivity to Mitomycin, which causes DNA–interstrand crosslinking." (PMID 17353918, 2007). "Importantly, BRCA1, BRCA2, and several associated genes — particularly members of the Fanconi anemia gene family — are transcriptionally regulated by the DREAM complex." (PMID 40841483, 2026). "In addition to its mutation in human cancers, BRCA2 is known to participate in the Fanconi DNA repair pathway, and some biallelic variants in BRCA2 are found in patients with clinical Fanconi anemia." (PMID 39767807, 2024). "Other predisposition syndromes, such as BRCA1-/BRCA2-related tumor predisposition syndrome, Fanconi anemia and Li Fraumeni syndromes, are sensitive to both IR and chemicals, as they interfere with different repair pathways that are also responsible for chemicals." (PMID 36899955, 2023). "The presence of BRCA2 pathogenic variants posed a risk of Fanconi anemia." (PMID 37761810, 2023). "Indeed, biallelic mutations in BRCA2 results in childhood Fanconi anemia (FANCD1), which is an autosomal recessive disease resulting in developmental abnormalities, bone marrow failure, and early-onset leukemia or solid tumors." (PMID 34456966, 2021). "BRCA2-null mice have an embryonic lethal phenotype, and biallelic germline mutations in BRCA2 are rare, but may result in a Fanconi anemia." (PMID 33503928, 2021). "Furthermore, the FANCD1 sub-group of DNA repair-defective Fanconi Anemia patients is actually the result of bi-allelic BRCA2 mutation." (PMID 34359565, 2021). "Interestingly, germline mutation rate of members of the Fanconi anaemia family of genes (including BRCA2, PALB2, BRIP1, RAD51C, FANCA, FANCI and FANCL) was 53.4% (31/58) among the patients with germline mutations in our cohort." (PMID 32091409, 2020). "However, it was shown that BRCA2-FANCD2 association has an independent function in the Fanconi Anemia pathway." (PMID 31191615, 2019). "Reversed forks are protected through the actions of a number of factors including the tumour suppressor genes BRCA1 (BRCA1, DNA repair associated) and BRCA2 (BRCA2, DNA repair associated), as well as other components of the homologous recombination and Fanconi anaemia (FA) repair pathways." (PMID 30525090, 2018). "Such a defect, which may be compatible with limited HR execution, could explain the hypomorphic nature of bi-allelic mutations affecting the C-terminus of BRCA2 in patients with Fanconi anemia." (PMID 29309696, 2018). "In bladder cancer samples, the tool also revealed a previously unknown role for inherited mutations in BRCA2 and other DNA repair genes in the so-called Fanconi anemia pathway." (PMID 29263839, 2017). "At least three Fanconi Anemia cases are attributable to BRCA2/FANCD1 homozygous mutations." (PMID 27836010, 2016). "Additionally, this child was different from children with Fanconi anemia and childhood cancer in that he was 8 years old at medulloblastoma presentation, whereas medulloblastomas in BRCA2-mutated Fanconi anemia patients typically present before age 5 years." (PMID 26380221, 2015). "Fanconi anaemia is caused by biallelic (or X-chromosome-linked) inactivation of 1 out of 13 FA genes, including BRCA2 (FANCD1)." (PMID 18475298, 2008). "Moreover, rare bi-allelic mutations in BRCA2 can give rise to Fanconi anaemia." (PMID 39711301, 2024). "Fortunately, the biallelic presence of pathogenic BRCA2 alleles is associated with a specific fully penetrant clinical phenotype known as Fanconi anemia and may present as microcephalic primordial dwarfism in severe cases, whereas biallelic BRCA1 mutation is presumably lethal in humans." (PMID 27884173, 2016).